EZH2 (enhancer of zeste 2 polycomb repressive complex 2 subunit)
Diseases named in the same sentence as EZH2 in open-access papers (continued):
Sharing a sentence is not in itself a finding about the gene and the disease.
tumor (continued). "Overall, inhibiting EZH2 directly via the occupation of the site for S-adenosyl-L-methionine (SAM) in the EZH2′s binding pocket inhibits MNA NB cell and tumor growth." (PMID 38069407, 2023). "Nine genes including NSD2, MLL2, and JARID1C act as drivers in only one to three tumor types, and the rest nine genes including DNMT3A, EZH2, and SET2 drive 5–18 malignancies." (PMID 37620312, 2023). "The histone methyltransferase, Enhancer of Zeste Homolog 2 (EZH2) suppresses normal skeletal muscle differentiation and is highly expressed in RMS tumours." (PMID 37858275, 2023). "Inhibiting EZH2 removes the trimethylation marks and relieves the suppression of PIK3IP1, which is then able to inhibit the PI3K/AKT pathway, leading to tumour suppression." (PMID 38275587, 2023). "reversed EZH2‐mediated H3K27me3 using the small molecule compound EPZ011989, thereby inhibiting SCLC tumor growth." (PMID 37220590, 2023). "miR-34a, a tumor suppressor gene governing apoptosis and cell cycle obstruction, can be arrested due to H3K27 trimethylation of its promoter by EZH2 in pancreatic ductal adenocarcinoma." (PMID 35087589, 2022). "The lncRNA HITT directs EZH2 to promoter of HIF-1α to form RNA–DNA triplex, leading to HIF-1α down-regulation and subsequent tumor suppression." (PMID 35236381, 2022). "Viral mimicry is thought to be an important mediator of tumor innate immunity in response to epigenetic therapies such as DNMT inhibitors, histone deacetylase inhibitors, CDK4/6 inhibitors and EZH2 inhibitors." (PMID 36923279, 2022). "In the previous study, we reported that EZH2 can transcriptional suppressed PTEN expression and thus promoting tumor stemness and growth by activating AKT signaling pathway." (PMID 36401232, 2022). "Ultimately, this study provides evidence of a direct link between EZH2 and CCF–cGAS activation in tumor cells." (PMID 35163710, 2022). "The EZH2 signaling is vital for appropriate function of cytotoxic CD8 + T cells in TME and preventing tumor progression." (PMID 35236381, 2022). "Enhancer of zeste homolog 2 (EZH2), a PRC2 component, mediates histone H3 lysine 27 trimethylation and represses tumor production of CXCL9 and CXCL10." (PMID 34385592, 2022). "We experimentally validate the oncogene PDIA3P1, and tumor-suppressor RRN3P3, which promote the RNA and protein expression of their targeted immune-involved genes AKT1 and EZH2 via miR-34a-5p and miR-26b-5p, respectively." (PMID 36438489, 2022). "This was associated with decreased expression of the SMYD2 protein substrates EZH2, p65, p-mTOR, and p-MAPK in OC-PF-treated primary tumor samples compared to in the placebo control-treated animal tumors." (PMID 35884603, 2022). "Combined targeting of IGF2BP1, EZH2, and Myc, a transcriptional activator of EZH2 and well-known target of IGF2BP1 cooperatively induces tumor cell apoptosis." (PMID 35565249, 2022). "In triple negative breast cancer (TNBC), EZH2 was shown to downregulate TET1 expression and consequently inhibited tumor senesence and apoptosis, indicating that TET1 is a tumor suppressor, also in TNBC." (PMID 35646706, 2022). "According to the results, MiR-26b-5p expression was significantly reduced while circ_ANKIB1 and EZH2 expressions were elevated in KHOS and U2OS tumor cell lines compared to the hFOB1.19 normal cell line." (PMID 35264070, 2022). "For example, phosphorylation of Enhancer of Zeste Homolog 2 (EZH2) results in STAT3 methylation, increasing STAT3 activity, and this interaction preferentially occurs in GSCs relative to other tumor cells." (PMID 35954407, 2022). "We discovered that simultaneous inhibition of the histone methyltransferases G9A and EZH2 activates the CXCL10–CXCR3 axis and increases homing of intratumoral effector lymphocytes and natural killer cells while suppressing tumor-promoting FoxP3+ CD4 T cells." (PMID 35131874, 2022).
tumor (continued). "In addition, inhibition of EZH2 methyltransferase was found to promote PD-1 expression on macrophages, and the combination of EZH2 inhibitors and anti-PD-1 antibodies could achieve better anti-tumor efficacy." (PMID 35663968, 2022). "We also constructed a prognostic nomogram model, which included EZH2, GRPEL2, NDRG1, and the tumor size." (PMID 36686830, 2022). "GSK343, a selective EZH2 inhibitor, successfully inhibited H3K27 methylation in an in vivo mouse model and reduced tumor growth." (PMID 35954407, 2022). "Moreover, EZH2-mediated histone H3 methylation of HIF1α in macrophages leads to the silence of HIF1α expression and reprograms the immune suppressive microenvironment to the facilitative one, which alleviates the tumor burden and prolongs the overall survival of mice implanted with tumor." (PMID 35693795, 2022). "As epigenetic silencing decreases Th1-type chemokines to limit effector T-cell trafficking to the tumor, ICB in combination with inhibitors of EZH2 and DNMT1 slows cancer progression in ID8 ovarian cancer and CT26 colon models." (PMID 34385592, 2022). "Co-inhibition of both EZH2 and EGFR elicited a synergic effect on tumor growth suppression in CRC by triggering autophagy and inducing apoptosis." (PMID 35449124, 2022). "Again, administration of DZNep, which depleted EZH2 and MYC(N), markedly inhibited proliferation of all the tumor cells examined, while administration of the enzymatic inhibitor GSK126 largely exhibited minimal effect." (PMID 35013218, 2022). "With DNA damage induced by alkylating agents in tumor cells, PARP1 reduces the affinity of EZH2 for H3K27 sites and inhibits its enzymatic activity through PARylation, while poly ADP-ribose glycohydrolase (PARG) can reverse this effect." (PMID 36263120, 2022). "SNHG1 interacting with proteins, such as hnRNPL, EZH2, and MART3, to modulate tumor progression have been reported in various cancer types." (PMID 36130928, 2022). "We used a chemical EZH2 inhibitor, GSK126, small interfering RNAs, and a CRISPR/Cas9 knockout approaches in a series of DMG tumor cell lines to investigate metabolic treatment responses by proteomic analysis." (PMID 35300150, 2022). "EZH2 is one of the most important members of polycomb family which is upregulated in ESCC and promotes tumor development." (PMID 36316365, 2022). "EZH2 has been reported to promote the recurrence and progression of HCC and thus is an important factor for tumor growth." (PMID 35627262, 2022). "EZH2 controls genes involved in EMT and invasion targeting PRC2 potentially affects tumor metastasis and angiogenesis." (PMID 36316365, 2022). "A recent experiment revealed that EZH2 upregulation by circPVT1 results in high infiltration of macrophages in TME and enhancing tumor progression." (PMID 35236381, 2022). "Gene expression profiling performed in primary EwS tumor and in stem cells expressing EWSR1-FLI1 found that, downstream of EZH2, HOX genes disrupt developmental transcription programs and thus provide the stemness feature for EwS tumors." (PMID 35740349, 2022). "The EZH2 catalytic SET domain catalysing histone 3 lysine 27 tri‐methylation (H3K27me3) is reported to bind and silence specific tumour suppressor genes." (PMID 35257481, 2022). "EZH2 regulated STAT3 and FoxO1 signaling to promote tumor glycolysis in human oral squamous cell carcinoma cells." (PMID 35892859, 2022). "Both EZH2 and PARP1 are multitargets, so targeting tumor cells through novel drug loading and delivery systems is one of the solutions to improve the existing therapeutic efficacy in this case." (PMID 36263120, 2022).
tumor (continued). "Therefore, therapeutics targeting the role of MEIS1 in oxaliplatin resistance are developed and our results suggest that the combination of oxaliplatin with either ELFN1-AS1 ASO or EZH2 inhibitor GSK126 could largely suppress tumor growth and reverse oxaliplatin resistance." (PMID 35351858, 2022). "We found that the oncogene PDIA3P1, and tumor-suppressor RRN3P3, promote the RNA and protein expression of their targeted immune-involved genes AKT1 and EZH2 via miR-34a-5p and miR-26b-5p, respectively." (PMID 36438489, 2022). "Together, our data suggest that the combination of an OV backbone armed with amiR-4 and the small-molecule inhibitor GSK126 facilitates tumour cell death via a synthetic lethal interaction between ARID1A and EZH2." (PMID 35393414, 2022). "As an important epigenetic regulator of transcription mediated by histone methylation, EZH2 interacts with PARP through DNA homologous recombination, DNA replication, posttranslational modification, tumor immunity and other aspects." (PMID 36263120, 2022). "This tumor suppressive microRNA targets the transcriptional repressors, EZH2 (Enhancer of Zeste Homolog 2, the component of polycomb repressive complex 2 (PRC2)) and Snail, thereby preventing EMT." (PMID 35813818, 2022). "Pharmacological inhibition of EZH2 reverses PRC2-mediated MHC-1 silencing by suppressing the repressive H3K27me3, leading to re-establishment of effective T-cell-mediated anti-tumor immunity." (PMID 36048239, 2022). "came to the identical conclusion, demonstrating that genetic or pharmacological inhibition of EZH2 induces re-expression of chemokine CXCL10 in HCC and therefore promotes migration and infiltration of NK cells into the tumor." (PMID 36685594, 2022). "Selective inhibition of Enhancer of Zeste Homolog 2 (EZH2), using CPI-1205, in a murine MC-38 cancer model disrupted the immunosuppressive function of tumor infiltrating Tregs, skewing their response towards a more pro-inflammatory phenotype." (PMID 36551637, 2022). "We further confirmed EZH2 and MYCN protein levels by immunoblot in 18 primary tumor samples isolated from TH-MYCN mice." (PMID 35013218, 2022). "Although PRC2 has oncogenic properties in most tumors, it has been shown that EZH2 and other PRC2 subunits also have tumor-suppressive functions in some types of tumors." (PMID 36076977, 2022). "We further s.c. injected stably transfected cells (Hep3B, Hep3B/EZH2, Hep3B/EZH2/pcDNA6, and Hep3B/EZH2/Dicer) into SCID mice and determined the tumor volume after vehicle or sorafenib administration." (PMID 35253323, 2022). "Taken together, our results indicate that EZH2 methylated SMAD3 at K53 and K333, triggering tumor metastasis." (PMID 35085106, 2022). "Together our results suggest that EZH2 has a tumor suppressor function in DMG and warrants caution in clinical translation of EZH2 inhibitors to treat patients with DMG." (PMID 35395831, 2022). "EZH2 increases H3K27me3 in the promoter of PTEN thus silencing PTEN and activating the threonine protein kinase B (AKT)/mTOR pathway, promoting GBM tumor cell proliferation and metastasis." (PMID 35572545, 2022). "Treatment of solid tumors with EZH2 inhibitors increases the recruitment and function of CD4+ and CD8+ effector T cells by induction of an inflammatory phenotype within tumor-infiltrating Tregs." (PMID 35795673, 2022). "The multivariate regression analysis showed that EZH2, NDRG1 and GRPEL2, as well as the tumor size were independent factors for the prognosis of HCC." (PMID 36686830, 2022). "In this study, compared with doxorubicin, dual inhibition of H3K9me2 and H3K27me3 with the G9a inhibitor, UNC0642, and the EZH2 inhibitor, UNC1999, promoted tumor cell senescencewithout triggering SASP." (PMID 35409271, 2022). "An enhancement of miR‐126‐5p and KLF2 while reductions in EZH2 and BIRC5 were seen in tumour tissues of nude mice treated with X‐ray alone or combined with lv‐miR‐126‐5p." (PMID 35322532, 2022).
tumor (continued). "Specifically, in GBM stem cells, AKT phosphorylates EZH2, and then it methylates STAT3 leading to enhanced STAT3 activity, which promotes GSC self-renewal and tumor malignancy." (PMID 35197928, 2022). "Consistent with the genetic depletion of EZH2, we observe a visible decrease of peritoneal metastasis following daily oral administration of EPZ6438 (250 mg/kg) though primary tumor burden remains the same in both the control and treatment group." (PMID 36446780, 2022). "Depletion of key PCa-related oncogenic proteins c-Myc and EZH2 upon genetic and pharmacological inhibition of HSP60 and ClpP functions further supports a critical role of the UPRmt in tumor growth and progression." (PMID 35653190, 2022). "Other selective inhibitors of EZH2 such as PF-06821497, GSK2816126, are also reported to reduce tumor growth and progression in preclinical models." (PMID 35438143, 2022). "Epigenetic alterations relating to histone methylation (KMT2D, KMT2C, EZH2), histone acetylation (CREBBP, EP300), and DNA methylation (TET2) play an important role in tumor progression for FL and DLBCL." (PMID 36497332, 2022). "A study also demonstrated that EZH2 expression and H3K27me3 abundance are concomitantly raised in human HCC by comparison with non-tumor livers." (PMID 34545456, 2022). "That EZH2 can act as an oncogene or as a tumour suppressor is seen in AML, where EZH2 expression is required for maintenance of the disease but acts as a tumour suppressor at the induction stage." (PMID 35406676, 2022). "Downregulation of EZH2 decreases the levels of H3K27me3, displaces BMI1, and activates p16Ink4a transcription, which promotes the tumor cell senescence." (PMID 35409271, 2022). "As expected, administration of DZNep, which depleted EZH2 and MYCN, markedly inhibited proliferation of all the tumor cells examined, while administration of the enzymatic inhibitors (GSK126 and EPZ6438) exhibited minimal effects on Kelly and BE-2C cells." (PMID 35013218, 2022). "Here, we found that inhibition of EZH2 with EPZ6438 and GSK126 suppressed CRC proliferation and growth in a model of 2D and 3D spheroids in vitro, but only EPZ6438 exerted a tumor inhibition effect on tumor-bearing mouse." (PMID 35432300, 2022). "In contrast to the PBT24 tumor, the SF8628 tumor’s PCNA and EZH2 expressions were sensitive to 2.5 mM MgDCA." (PMID 36142368, 2022). "Moreover, we examined whether EZH2 is involved in mediating CRPC tumor cell response to DNA damage." (PMID 36408179, 2022). "Signaling of both EZH2 and TGFB was found to be crucial for EMT of tumor cells and tumor metastasis." (PMID 35085106, 2022). "EZH2, GRPEL2, NDRG1, and the clinical factor of tumor size, were included in a nomogram for visualizing a prognostic model of HCC." (PMID 36686830, 2022). "It has been reported that, when EZH2 was knocked down in PCa, IFNGR1 expression was restored, and when IFN therapy was applied, significant activation of IFN-JAK-STAT1 tumor suppressor signaling occurred." (PMID 36358967, 2022). "Therefore, inhibiting the enzymatic activity of EZH2 alone may not sufficient to prevent the growth of tumor cells with high expression and/or mutation of EZH2." (PMID 33794893, 2021). "EZH2-mediated methylation has been demonstrated to repress T helper 1 (Th1) chemokines, CXCL9 and CXCL10, resulting in reduced T-cell recruitment to the tumor microenvironment." (PMID 34140011, 2021).
tumor (continued). "Similar to EZH2, EHMT2 inhibits the transcription of tumor suppressor genes by promoting the methylation and dimethylation of H3K9me1/3K9me2." (PMID 34409024, 2021). "In vivo, tazemetostat inhibits tumor growth in xenograft-bearing mice with EZH2-mutant NHL, resulting in complete and sustained tumor regressions with lower H3K27me3 levels." (PMID 33761979, 2021). "In contrast to its obvious tumor-promoting activities in established PDAC, EZH2 protects acinar cells from malignant transformation." (PMID 34943970, 2021). "Thus, EZH2 not only controls gene silencing programs together with other chromatin remodelers, but can also regulate demethylation and deacetylation programs to orchestrate which metabolic pathways are enhanced for obtaining energy and precursors and which are maintained by the tumor cell." (PMID 34072826, 2021). "The mRNA and protein expression levels of UHRF1, EZH2, TTF2, WHSC1 and RAD54L significantly correlated with tumor stage in NSCLC patients." (PMID 33658396, 2021). "Collectively, circGSK3B directly interacts with EZH2 to block the binding of EZH2 to the RORA promoter, leading to an increase in RORA expression and the suppression of tumor progression through Wnt signaling pathway regulation." (PMID 34666800, 2021). "H3K27me3 is a repressive mark established by the catalytic enzymatic subunit enhancer of zeste homolog 2 (EZH2) of the Polycomb Repressive Complex 2 (PRC2), while H3K27me3-induced TSGs silencing is a mechanism for tumor development." (PMID 34768895, 2021). "In fact, the contradictory roles of the TET enzyme as a tumor suppressor and as an oncogene have also been observed in other epigenetic regulators such as DNMT3A and EZH2." (PMID 34209564, 2021). "In terms of EMT and metastasis, FOXF1-AS1 acted as a protective factor and interacted with PRC2 components EZH2 to hinder self-renewal of NSCLC CSCs and reduce the number of stem-like cells, thus leading to impaired EMT capacity of tumor cells." (PMID 35047506, 2021). "The analysis of cBioPortal clinical data indicates that amplification of EZH2, SUZ12, and EED genes was not limited to one particular malignancy but varied between different tumor types." (PMID 34202528, 2021). "EZH2 functions as a tumor suppressor, clinically apparent by the poor prognosis of patients with AML/MDS with reduced EZH2 activity." (PMID 34944554, 2021). "An enhanced macrophage infiltration into EwS tumors following the transfer of PRKCB and CCND1 transcripts could promote tumor growth, potentially by increasing the density of macrophages in tumors to amplify the immunosuppressive effects of their proinflammatory cytokines triggered by EZH2 and DKK2." (PMID 34604225, 2021). "In summary, our findings show that the combined application of GSK126 and 5-Aza synergistically inhibited EZH2 and DNMT3B to derepress the expression of TCF3, and profoundly blocked EC tumor progression in mouse models." (PMID 34175897, 2021). "Intriguingly, EZH2 expression is elevated in tumor-infiltrating Tregs, and pharmacological inhibition of EZH2 destabilize FOXP3 expression and slows tumor growth through enhancement of the recruitment and function of CD8+ and CD4+ T cells." (PMID 34069564, 2021). "EZH2 is the enzymatic catalytic subunit of the polycomb-repressive complex 2 (PRC2) that represses transcription of multiple genes, including tumor-suppressors." (PMID 34298609, 2021). "In both murine and human tumour cells, HOTAIR‐sbid impaired the ability of HOTAIR to bind Snail and, in turn, trigger H3K27me3/EZH2‐mediated repression of Snail epithelial target genes." (PMID 34296520, 2021). "In recent studies, enhancer of zeste homolog 2 (EZH2), the main enzyme of the gene repressor complex Polycomb 2 (PRC2), has been shown to play an important role in tumor development and progression." (PMID 34072826, 2021). "The PRC2 component EZH2 is essential for GSC maintenance and its pharmacological or molecular inhibition impairs GSC-driven tumor growth." (PMID 34885210, 2021).